DNAAF6 (dynein axonemal assembly factor 6)
Description:
Plays a role in cytoplasmic pre-assembly of axonemal dynein.
Synonyms: CXorf41; PIH1D3; MGC35261; NYSAR97; TWISTER; CILD36
Tractability: No criterion of Open Targets' tractability assessment is met for any kind of drug.
Gene: Protein-coding gene on chromosome X (107,206,611 to 107,244,247, forward strand). Ensembl gene ENSG00000080572.
Subcellular location: Cytoplasm; Golgi apparatus, trans-Golgi network
Subcellular location (Human Protein Atlas): Acrosome; Golgi apparatus; Primary cilium; Basal body; Cytosol; Equatorial segment; Nucleoplasm; Primary cilium tip
Gene Ontology:
Molecular function: dynein intermediate chain binding; protein binding; protein-folding chaperone binding
Biological process: axonemal dynein complex assembly; cilium movement; flagellated sperm motility; inner dynein arm assembly; outer dynein arm assembly
Cellular component: cytoplasm; Golgi apparatus; trans-Golgi network
Gene-disease validity (ClinGen):
ClinGen rates the evidence that DNAAF6 causes each of these diseases.
ciliary dyskinesia, primary, 36, X-linked (X-linked): Definitive.
Homologues: Orthologues: chimpanzee DNAAF6 (99% identical), macaque DNAAF6 (92% identical), dog DNAAF6 (74% identical), pig DNAAF6 (71% identical), guinea pig DNAAF6 (70% identical), rat Dnaaf6 (62% identical), mouse Dnaaf6 (61% identical), mouse Dnaaf6rt (60% identical), tropical clawed frog dnaaf6 (39% identical), zebrafish dnaaf6 (39% identical), Drosophila melanogaster Dnaaf6 (29% identical).
Diseases named in the same sentence as DNAAF6 in open-access papers:
DNAAF6 is named in the same sentence as 14 diseases in open-access papers, as found by Europe PMC text mining. Sharing a sentence is not in itself a finding about the gene and the disease. The quoted sentences say what the papers report.
primary ciliary dyskinesia (5 papers, 2017 to 2025). A rare, genetically heterogeneous, primarily respiratory disorder characterized by chronic upper and lower respiratory tract disease. "Since the first association of DNAAF6 with ciliary dyskinesia in humans in 2017, 15 probands from seven publications have been reported, harboring 15 distinct variants associated with outer and inner dynein arm defects." (PMID 41480157, 2025). "Dynein axonemal assembly factor 6 (DNAAF6), a causative gene of primary ciliary dyskinesia, was isolated as an interacting protein with La ribonucleoprotein 6 (LARP6) that regulates ciliogenesis in multiciliated cells (MCCs)." (PMID 38762183, 2024).
ciliopathy (2 papers, 2020 to 2023). A genetic disorder of the cellular cilia or the cilia anchoring structures, the basal bodies, or of ciliary function. "The other is the TWI1 protein (predicted molecular weight = ~ 20590), and defects in the TWI1 orthologue (DNAAF6/PIH1D3) also cause the ciliopathy." (PMID 33141819, 2020).
DNAAF6 also shares sentences with these, for which no sentence is quoted: male infertility (3 papers); asthenozoospermia (2); cancer (2); Hydrocephalus (2); situs inversus (2); asthma (1); colorectal cancer (1); communicating hydrocephalus (1); embryonic carcinoma (1); immune disease (1); infertile (1); tumor (1).